ENSG00000255730 (novel protein)
Gene: Protein-coding gene on chromosome 19 (41,350,853 to 41,425,001, forward strand). Ensembl gene ENSG00000255730.
Genetic constraint (gnomAD): Loss-of-function variants: 43 observed, 53.08 expected, observed/expected ratio (o/e) 0.81, 90% interval 0.63 to 1.04. Missense variants: 554 observed, 681.99 expected, observed/expected ratio (o/e) 0.81, 90% interval 0.76 to 0.87. Synonymous variants: 243 observed, 270.96 expected, observed/expected ratio (o/e) 0.9, 90% interval 0.81 to 1.